IL17A (interleukin 17A)
Diseases named in the same sentence as IL17A in open-access papers (continued):
Sharing a sentence is not in itself a finding about the gene and the disease.
typhoid fever (3 papers, 2014 to 2024). A bacterial infectious disorder contracted by consumption of food or drink contaminated with Salmonella typhi. "Our previous studies have shown that MAIT cells displaying distinct cytokine patterns (i.e., IFN-γ+ TNF-α+ IL-17A- positive cells) were associated with protection against typhoid fever." (PMID 39372404, 2024).
Acanthamoeba infection (2 papers, 2023 to 2025). "Several cytokines, such as interferon-gamma (IFN-γ), interleukin (IL)-4, IL-10, IL-17A, IL-17F, and IL-22, are rapidly produced and secreted in response to Acanthamoeba infection." (PMID 40109888, 2025). "Several cytokines, for example, IFN-γ, IL-4, IL-10, IL-17A, IL-17F, and IL-22, were reported to rapidly produce and secrete in response to the Acanthamoeba infection but not IL-1β cytokine." (PMID 40109888, 2025).
acute chest syndrome (2 papers, 2019 to 2024). A vaso-occlusive crisis of the pulmonary vasculature occurring in patients with sickle cell disease. "In fact, elevated IL-17A is associated with absence of acute chest syndrome in SCD participants, indicating a protective role." (PMID 38361924, 2024).
adenoid hypertrophy (2 papers, 2020 to 2026). "A previous study showed that pneumococcal carriage initiates an interleukin (IL)-17A-mediated immune response in nasopharyngeal adenoids, which might be associated with adenoidal hypertrophy that leads to mouth breathing." (PMID 33154739, 2020).
age (2 papers, 2022 to 2026). A temporal measurement of the time period elapsed since an identifiable point in the life cycle of an organism. "This reduces pulmonary Th17 cells and IL-17A, thereby suppressing Col-I synthesis in pulmonary fibroblasts and ultimately alleviating age-related PF." (PMID 42257498, 2026).
anthrax (2 papers, 2015). "Conversely, recent work has suggested that exposure of human ex vivo cells to ET at low concentrations is capable of promoting a Th17 response, and studies in mice have further indicated a key role for IL-17A in protective immunity against inhalational anthrax." (PMID 26075052, 2015). "IL-17A release in response to acute infection is predominantly from innate immune cells rather than Th17 cells and neutrophils were shown to be the main cellular source of IL-17 in a murine model of inhalational anthrax." (PMID 25822228, 2015).
arbovirus infection (2 papers, 2021 to 2022). A viral infection that is transmitted by an arthropod. "Considering the BBB permeability is a crucial early event for neurological damage, the ratio of IL-22/IL-17A levels in serum seemed to be an accurate serological marker for neurological assessment risk in arbovirus infections." (PMID 33776990, 2021).
benign ovarian tumor (2 papers, 2019 to 2020). "The PF IL-17A level in OC patients was higher (p < 0.0001) than that in women with benign ovarian tumors, indicating its synthesis in OC microenvironment." (PMID 32148497, 2020).
bone metastasis (2 papers, 2014 to 2015). Transfer of a neoplasm from its primary site to bones. "When treated with anti-IL-17A antibody, only 40% (4 out 10) and 30% (3 out of 10) developed lung and bone metastasis respectively." (PMID 24674692, 2014).
Bovine mastitis (2 papers, 2017 to 2021). INFLAMMATION of the UDDER in cows. "The results of the present study provided the first evidence that the IL-17A promoter polymorphism, whose function is still unclear, is significantly associated with cytokine IL-4 of bovine mastitis." (PMID 28101335, 2017).
Burkitt lymphoma (2 papers, 2020 to 2021). A rare form of malignant mature B-cell non-Hodgkin lymphoma. "Interestingly, IFN-γ and IL-17A were recovered after transfection of Burkitt's lymphoma cells with siRNAs targeting NLRP11." (PMID 32832566, 2020). "Furthermore, cocultures of NLRP11-expressing Burkitt's lymphoma cells and naïve human peripheral CD4+ T lymphocytes had reduced IFN-γ and IL-17A production, whereas IL-13 and IL-10 cytokines did not change." (PMID 32832566, 2020).
carditis (2 papers, 2024 to 2025). "In this study, we have demonstrated that the BPTx induced IFN‐γ+ and IL‐17A+ T‐cell responses are essential for the development of carditis." (PMID 40642941, 2025).
cerebral amyloid angiopathy (2 papers, 2022 to 2025). "Along with this, brain IL-17A overexpression decreased soluble Aβ levels in the HPC and cerebrospinal fluid, drastically reduced cerebral amyloid angiopathy, and caused anxiolytic and spatial memory-enhancing effects in an AD mouse model." (PMID 40563933, 2025).
cerebrovascular diseases (2 papers, 2025). "Dysregulation of the Th17/IL-17A response represents a fundamental pathogenic mechanism in neurological and cerebrovascular diseases, promoting neuroinflammation through infiltration into the CNS, microglial activation, and disruption of the blood–brain barrier." (PMID 41357230, 2025).
cervical diseases (2 papers, 2015 to 2019). "Our results presented here show that the control women had both higher levels of IL-17A and IFN-γ in LST+ samples and also in HPV16 peptide-specific responses than the cases, indicating that Th17 might play an important protective role in HPV induced cervical diseases." (PMID 25990808, 2015).
Chagas cardiomyopathy (2 papers, 2017 to 2020). A disease of the cardiac muscle developed subsequent to the initial protozoan infection by trypanosoma cruzi. "Plasma IL-17A levels were measured by BD Cytometric Bead Array (CBA) in 240 patients with positive specific serology for Trypanosoma cruzi (T. cruzi) grouped as indeterminate (IND) and Chagas cardiomyopathy (CARD) forms." (PMID 28278264, 2017).
cholera (2 papers, 2023). "A marked increase in IL-17A and IFN-γ production was also noted in whole blood cultures from cholera patients after stimulation with a membrane protein preparation (MP) of cholera antigens." (PMID 37809062, 2023).
chondrosarcoma (2 papers, 2005 to 2021). A malignant cartilaginous matrix-producing mesenchymal neoplasm arising from the bone and soft tissue. "The chondrosarcoma cell line, SW1353, stimulated by the combined cytokines, IL-1β and IL-17A, was selected to evaluate the effects of KP extract and its major components at a cellular level." (PMID 33799537, 2021).
chronic pancreatitis (2 papers, 2020 to 2021). A chronic inflammatory process causing damage and fibrosis of the pancreatic parenchyma. "This study also showed that decreased IL-17A+ cells in the pancreas alleviates chronic pancreatitis-associated inflammation and fibrosis via stimulation of interferon gene signaling, which suggests that Th17 is involved in chronic inflammation of the pancreas." (PMID 32296650, 2020). "Currently, an anti-IL-17A antibody reduces the impact of IL-17A on pancreatic stellate cells and attenuates pancreatic fibrosis in chronic pancreatitis." (PMID 34594321, 2021). "A recent study showed that IL-17A+ cells were increased in human chronic pancreatitis tissues." (PMID 32296650, 2020).
Cm (2 papers, 2012 to 2018). "Interleukin-17A (IL-17A), as a new proinflammatory cytokine, has been shown to play a protective role in host defense against Chlamydia muridarum (Cm) infection." (PMID 22745717, 2012). "The results suggest that IL-17A can synergize with IFN-γ to enhance IFN-γ-mediated iNOS induction and NO production during Cm infection." (PMID 22745717, 2012). "To define the related mechanism, we investigated, in the present study, the effect of IL-17A on IFN-γ induced iNOS expression and NO production during Cm infection in vitro and in vivo." (PMID 22745717, 2012).
CNS demyelinating diseases (2 papers, 2013 to 2021). "We measured the CSF concentration of each cytokine in 20 AE patients, and compared IL-6 and IL-17A concentrations with 13 patients with CNS demyelinating diseases and 20 non-inflammatory controls." (PMID 34054854, 2021).
colorectal adenocarcinoma (2 papers, 2018 to 2025). The most common type of colorectal carcinoma. "The human colorectal adenocarcinoma epithelial cell line, HT-29, was utilized previously to show antibody neutralization of human IL-17A." (PMID 29329326, 2018).
condyloma acuminatum (2 papers, 2024 to 2025). "Through this case, we strongly suspect that anti IL-17A treatment may promote the onset and rapid progression of low-risk HPV-associated condyloma acuminatum." (PMID 38813385, 2024).
Darier disease (2 papers, 2023 to 2026). Darier disease (DD) is a keratinization disorder characterized by the development of keratotic papules in seborrheic areas and specific nail anomalies. "IL-17A inhibitors may play an important role in the management of Darier disease and represent a promising therapeutic option for pediatric patients, particularly in cases refractory to conventional therapies." (PMID 41646610, 2026). "IL-17A inhibitors have demonstrated benefit in adults with Darier disease." (PMID 41646610, 2026).
delayed hypersensitivity reactions (2 papers, 2024 to 2025). "The CHS reaction is mediated by CD4+T cells producing IL-17A and IFN-γ and is classified as a type IV hypersensitivity reaction, which characterizes many autoimmune disorders." (PMID 39247190, 2024).
Diarrhea (2 papers, 2019 to 2024). Abnormally increased frequency (usually defined as three or more) loose or watery bowel movements a day. "Results showed that horses in Diarrhea group had systematic inflammatory reactions which were indicated by the significant increased serum levels of LPS, IL-17A, lactic acid, and total protein compared to Control group (p = 0.0073, p = 0.0117, p < 0.0001, p = 0.0019, respectively)." (PMID 38711536, 2024). "Our analysis revealed significant positive correlations between Alkalibacterium, Lactobacillus, and Streptococcus were significantly positively correlated with LPS, Lactic acid, Total protein, Diarrhea score, and IL-17A, and Alkalibacterium was significantly negatively correlated with pH levels." (PMID 38711536, 2024).
dysentery (2 papers, 2022 to 2023). Acute inflammation of the intestine associated with infectious diarrhea of various etiologies, generally acquired by eating contaminated food containing toxins, biological derived from bacteria or other microorganisms. "Shigella-positive MSD (Shigella cases with and without dysentery) was associated with increased amounts of all the cytokines measured except IL-17A (gray filled columns) compared to EPEC with diarrhea." (PMID 35924851, 2022). "Increased levels of GM-CSF and reduced production of TNF-β, IL-1β, IL-17A, IL-16, IL-4, and IL-10 were distinct responses observed in Shigella-infected children with dysenteric diarrhea compared to Shigella without dysentery." (PMID 35924851, 2022). "Children with dysenteric Shigella exhibited significantly lower levels of TNF-β, IL-1β, and IL-17A but higher levels of GM-CSF than those without dysentery after adjustment for age and sex (blue circles)." (PMID 35924851, 2022).
enthesitis-related arthritis (2 papers, 2022). "The blocking of IL-17A was found to improve the course of JIA, leading to the approval of the use of the human anti-IL17A monoclonal antibody secukinumab in the treatment of the JIA subtypes juvenile psoriatic arthritis (JPsA) and enthesitis-related arthritis (ERA)." (PMID 36363508, 2022).
erythroderma (2 papers, 2017 to 2022). "In the case of very inflammatory and itchy form of scaly erythroderma, a biotherapy blocking IL-17A (such as Secukinumab or Ixekizumab) appears to be currently the best therapeutic option according to several case reports." (PMID 36619513, 2022). "In the case of a very inflammatory and itchy form of scaly erythroderma or ILC, a biotherapy blocking IL-17A (such as Secukinumab or Ixekizumab) appears to be currently the best therapeutic option to improve the permanent inflammatory condition of the skin and/or to prevent acute flares." (PMID 36619513, 2022).
Flavivirus Infections (2 papers, 2022 to 2025). Infections with viruses of the genus FLAVIVIRUS, family FLAVIVIRIDAE. "γδ T cells may contribute to the regulation of adaptive immunity through the secretion of IL-17A, thereby exerting an indirect antiviral effect against flavivirus infections." (PMID 40245023, 2025). "The expression of IL-17A in TBE patients observed in this study is in concordance with the reported data in WNND, suggesting a common cytokine pattern of IL-17A expression in neuroinvasive flavivirus infections that needs to be investigated further." (PMID 36366333, 2022).
frontotemporal dementia (2 papers, 2022 to 2025). Frontotemporal dementia (FTD) comprises a group of neurodegenerative disorders, characterized by progressive changes in behavior, executive dysfunction and language impairment, as a result of degeneration of the medial prefrontal and frontoinsular cortices. "Additionally, cerebrospinal fluid IL-17A levels have been proposed as a potential tool for the pre-mortem identification of tau pathology in frontotemporal dementia, further emphasizing the clinical relevance of this cytokine." (PMID 40141149, 2025).
ganglionitis (2 papers, 2015 to 2023). "Tenosynovitis occurs in a subset of patients with RA, even in patients with no metacarpophalangeal joint synovitis, and these patients could benefit from an anti-IL-17A therapeutic approach if they do not fully respond to the specific biologic agent." (PMID 37035302, 2023).
gastric disease (2 papers, 2017 to 2024). "It is known that pathogenic CD4+ T cells for the transfer EAE express cytokines including IFN-γ, IL-17A, and IL-6, and very strong stress alone induces gastric disease via p38 activation at the affected tissues by the activation of the vagal pathway." (PMID 28809157, 2017).
Hyperbilirubinemia (2 papers, 2026). An increased amount of bilirubin in the blood. "Univariate Cox regression indicated that elevated plasma IL-17A was significantly associated with poorer OS in the hyperbilirubinemia subset (HR = 1.63, 95% CI 1.04-2.55, P = 0.033)." (PMID 42023242, 2026). "Further stratification by median IL-17A levels showed that hyperbilirubinemia patients with high IL-17A had significantly worse OS (HR = 2.89, 95% CI 1.03-8.07, P = 0.035), whereas IL-17A levels had no significant impact in patients with normal bilirubin (P = 0.870)." (PMID 42023242, 2026).
hypertensive nephropathy (2 papers, 2020 to 2025). Kidney damage that results from chronically elevated blood pressure; complications include glomerular damage resulting in proteinuria and hematuria. "In this sense, in human renal biopsies of hypertensive nephropathy patients, positive IL-17A cells, mainly Th17 and γδ T cells, were found, suggesting the involvement of IL-17A in the progression of human kidney diseases." (PMID 32987705, 2020).
idiopathic intracranial hypertension (2 papers, 2021 to 2023). "This could be explained by the fact that most of our negative controls suffered from idiopathic intracranial hypertension, patients known to express a high level of IL-17A in the CSF." (PMID 34054854, 2021).
IgA vasculitis (2 papers, 2021 to 2025). "IL-17A inhibitors have also been reported as triggers of IgA vasculitis." (PMID 34299162, 2021).
infective endocarditis (2 papers, 2020 to 2022). Infective endocarditis (IE) is an infection of the inner lining of the heart chambers (endocardium) and valves. "High serum levels of IL‐17A and IL‐10 often preceded the radiographic diagnosis of infective endocarditis, suggesting potential utility for prioritising diagnostic radiographic imaging." (PMID 32082571, 2020). "High IL‐17A identified more patients who meet clinical study endpoints of antibiotic failure than were identified by infective endocarditis diagnosis, offering potential utility as risk stratification biomarkers to facilitate patient selection for clinical trials." (PMID 32082571, 2020). "High IL‐17A and IL‐10 identified more patients who developed microbiological failure or mortality than were identified by infective endocarditis diagnosis." (PMID 32082571, 2020). "We found that serum IL‐17A, IL‐10 and sE‐selectin are prognostic for persistent bacteraemia and infective endocarditis in patients hospitalised with S. aureus bacteraemia." (PMID 32082571, 2020).
influenza A (H1N1) (2 papers, 2017 to 2021). Viral infectious disease caused by the H1N1 strain of the influenza type A virus. "However, the cell types responsible for IL-17A production during the early stage of severe influenza A (H1N1) pdm09 infection remained unknown." (PMID 28912779, 2017). "The present study also reported the lack of association between SNPs in the IL6, IFNG, IL17A, and TGFB genes and disease severity of Influenza A(H1N1)pdm09 virus infection." (PMID 34946862, 2021). "In this study, we found that γδT cells (including the Vγ4+γδT subset) were rapidly recruited to the lungs and were the major source of lung IL-17A, which might mediate the development ALI and ARDS at the early stage during severe influenza A (H1N1) pdm09 virus infection in mice." (PMID 28912779, 2017).
invasive breast carcinoma (2 papers, 2022 to 2023). A carcinoma that infiltrates the breast parenchyma. "The median serum IL-17A concentration in women with early invasive breast cancer before surgery and during adjuvant therapy was 1.82 pg/ml (1.15-4.72) and 1.25 pg/ml (1.00-2.05), respectively, while the median serum IL-17A concentration in healthy controls was 1.05 pg/ml (0.65-1.48)." (PMID 37427128, 2023).
Klebsiella Infections (2 papers, 2012 to 2019). Infections with bacteria of the genus KLEBSIELLA. "Although lung-resident innate-like T cells did not constitutively express IL-17A as assessed by the hNGFR reporter, γδ T cells, iNKT cells and other CD3ε+ cells expressed hNGFR within 24 hr after Klebsiella infection or 8 hr after administration of IL-1β and/or IL-23." (PMID 22768117, 2012).
membranous nephropathy (2 papers, 2018 to 2023). "In patients with primary membranous nephropathy, increased expression of IL‐6 secreted by MDSCs expands MDSCs and increases Arg‐1 production for Th17 cell differentiation and IL‐17A production." (PMID 37382257, 2023). "Significantly higher frequency of CD4+/CXCR5+, CD4+/CXCR5+/ICOS+ and CD4+/CXCR5+/PD-1+ TFH cells, and higher serum levels of IL-17A, IFN-γ, IL-2, IL-10, IL-4 and IL-21 were detected in hepatitis B virus-associated membranous nephropathy patients compared to the healthy controls." (PMID 28770269, 2018).
monocytic leukemia (2 papers, 2017). "Previous reports demonstrated that IL-17A activated both STAT1 and STAT3 in human monocytic leukemia cells and keratinocytes and human keratinocytes, implying that IL-17A can induce M1 and M2 macrophage-related proteins via direct activation of both STAT1 and STAT3 in the skin of mouse." (PMID 28963556, 2017).
mucormycosis (2 papers, 2021 to 2025). "Regarding the adaptive immune response, it is known that patients with mucormycosis caused by R. oryzae, and R. pusillus exhibit an immune profile driven by lymphocytes, macrophages, and polymorphonuclear neutrophils (PMNs), triggering responses involving IFN-γ, IL-17A, and IL-10." (PMID 41156648, 2025).
Nb (2 papers, 2023 to 2024). "In both these studies, as in lung Nb infection, the source of IL-17A is γδ T cells." (PMID 37783278, 2023). "In neuroblastoma (NB), IL-17-producing γδT cells may produce some specific factors, mainly IL-17A, which may play a pro-tumor role." (PMID 39906741, 2024).
ocular sarcoidosis (2 papers, 2014 to 2022). A leading cause of inflammatory eye disease is sarcoidosis. "A study that compared the vitreous concentrations of inflammatory cytokines between PDR and ocular sarcoidosis reported that IL-4, IL-17A, IL-31, and TNFα were significantly elevated in PDR, indicating the involvement of Th2 and Th17-related immune responses in the pathogenesis of PDR." (PMID 35806888, 2022).